JMJD1C (jumonji domain containing 1C)
Description:
Demethylates lysine in proteins, such as STAT3 or MDC1 (By similarity). Demethylates MDC1, thereby promoting MDC1-RNF8 interaction and facilitating RNF8-dependent MDC1 ubiquitination essential for double-strand break (DSB) repair. Demethylation of STAT3 at 'Lys-140' facilitates its interactions with the phosphatase PTPN6 and restrains STAT3 activation (By similarity). It is uncertain whether JMJD1C removes methyl groups from histone proteins as the other JMJD1/KDM3 proteins do. Nevertheless, JMJD1C may act as a context-specific histone demethylase. Implicated in lipogenic gene transcription in the liver, where USF1 recruits JMJD1C to lipogenic promoters in response to insulin or feeding stimuli, thereby potentially promoting H3K9me2 demethylation and enhancing chromatin accessibility. Post-translational modifications may regulate JMJD1C's enzymatic activity, contributing to its context-specific functions. Alternatively, JMJD1C may influence chromatin regulation indirectly, acting as a scaffold or co-regulator that recruits or stabilizes other active demethylase complexes modifying histone marks. Plays an indispensable role in spermatogenesis (By similarity). [Isoform 3]: Coactivator of androgen receptor.
Synonyms: TRIP-8; KDM3C; KIAA1380; TRIP8; DKFZp761F0118; FLJ14374
Tractability: Small molecule: a structure with a bound ligand is known; a high-quality ligand is known. PROTAC: UniProt records ubiquitination sites on it; ubiquitination databases record sites on it; its protein half-life has been measured; a small molecule that binds it is known.
Target class: Epigenetic regulator; Jumonji domain-containing; Eraser; Lysine demethylase
Gene: Protein-coding gene on chromosome 10 (63,167,221 to 63,521,850, reverse strand). Ensembl gene ENSG00000171988.
Subcellular location: Nucleus; Nucleus (Isoform 3)
Subcellular location (Human Protein Atlas): Nucleoplasm; Cytosol
Pathways (Reactome):
Hemostasis: Factors involved in megakaryocyte development and platelet production
Gene Ontology:
Molecular function: histone H3K9 demethylase activity; protein binding; protein demethylase activity; nuclear thyroid hormone receptor binding; transcription coregulator activity
Biological process: blood coagulation; lipid biosynthetic process; plasma cell differentiation; regulation of DNA-templated transcription; regulation of transcription by RNA polymerase II; chromatin remodeling
Cellular component: nucleus; histone deacetylase complex; nucleoplasm
Genetic constraint (gnomAD): Loss-of-function variants: 22 observed, 200.49 expected, observed/expected ratio (o/e) 0.11, 90% interval 0.077 to 0.16. The upper end of that interval is the gene's LOEUF score, 0.16, which puts it in group 1 of 6, group 1 being the genes least tolerant of losing a copy. Missense variants: 2,413 observed, 2,711.4 expected, observed/expected ratio (o/e) 0.89, 90% interval 0.86 to 0.92. Synonymous variants: 932 observed, 942.12 expected, observed/expected ratio (o/e) 0.99, 90% interval 0.94 to 1.04.
Homologues: Orthologues: chimpanzee JMJD1C (99% identical), macaque JMJD1C (99% identical), dog JMJD1C (92% identical), pig JMJD1C (91% identical), rabbit JMJD1C (91% identical), guinea pig JMJD1C (90% identical), mouse Jmjd1c (86% identical), rat Jmjd1c (84% identical), tropical clawed frog jmjd1c (67% identical), zebrafish jmjd1cb (58% identical), Drosophila melanogaster Kdm3 (12% identical). Paralogues in human: KDM3B (25% identical), KDM3A (20% identical), HR (13% identical).
Diseases named in the same sentence as JMJD1C in open-access papers:
JMJD1C is named in the same sentence as 69 diseases in open-access papers, as found by Europe PMC text mining. Sharing a sentence is not in itself a finding about the gene and the disease. The quoted sentences say what the papers report.
leukemia (23 papers, 2015 to 2025). A malignant (clonal) hematologic disorder, involving hematopoietic stem cells and characterized by the presence of primitive or atypical myeloid or lymphoid cells in the bone marrow and the blood. "While loss of JMJD1C was found to substantially decrease leukemic stem cell (LSC) frequency and induced differentiation of MLL-AF9-, HOXA9-, and AML1-ETO-driven leukemia, JMJD1C loss led to only minor defects in blood homeostasis and hematopoietic stem cell (HSC) self-renewal." (PMID 39450904, 2025). "In summary, we have revealed a molecular mechanism underlying the general requirement for JMJD1C in multiple types of leukemia with completely different oncogenic mutations and also uncovered how an enzymatic activity-independent function of JMJD1C regulates the function of a key TF." (PMID 39450904, 2025). "In addition, a recent prior unbiased proteomic analysis of AE‐associated proteins identified a JmjC domain‐containing JMJD1C as a component that physically interacts with AE to facilitate AE‐induced leukemia." (PMID 34938963, 2021). "Our study provides insights into the molecular mechanism by which JMJD1C regulates gene expression and reveals a potentially general transcriptional regulation mechanism shared by different types of leukemia." (PMID 39450904, 2025). "Toward this goal, we first identify RUNX1 as a key TF that recruits JMJD1C to chromatin, a mechanism shared by multiple types of leukemia." (PMID 39450904, 2025). "We previously identified specific JMJD1C inhibitors that can preferentially kill MLLr AML or leukemia stem cells." (PMID 36429088, 2022). "Among them, the jumonji and zinc finger domains of JMJD1C were found by a CRISPR/Cas9-based screening system to be especially critical for leukemia." (PMID 36429088, 2022). "Taking a bioinformatic approach, we provide evidence that genes with the broadest H3K79me2 domain have known roles in leukemia (e.g., JMJD1C)." (PMID 36139405, 2022). "Dysregulated JMJD1C has been found previously in different diseases such as leukemia and esophageal cancer." (PMID 34586733, 2021). "JMJD1C is required for the maintenance of both leukemia cells and leukemic stem cells, serving as a potential therapeutic target of acute myeloid leukemia." (PMID 33289299, 2021). "In this study, JMJD1C was one of the top hits along with other well-characterized leukemia driver genes, including HOXA9 and HOXA10." (PMID 32806592, 2020). "Another in vitro shRNA library screen targeting epigenetic factors (898 constructs targeting 319 chromatin regulators) also found JMJD1C to be the highest scoring hit in MLL-AF9 leukemia." (PMID 32806592, 2020). "JMJD1C depletion induces a growth defect that is primarily attributed to the increase in apoptosis of leukemia cells from either mouse or human." (PMID 32625104, 2020). "In leukemia cells, Runx1 (Runt-related transcription factor 1) directly interacts with and recruits JMJD1C to target genes." (PMID 32625104, 2020). "JMJD1C is required for the self-renewal of leukemia stem cells (LSCs) of AML but not normal HSCs, and it has been implicated in the function of LSCs in MLL-AF9-driven leukemia, too." (PMID 40282457, 2025). "Our findings demonstrate a previously unappreciated role for the non-catalytic function of JMJD1C in transcriptional regulation, underlying a mechanism shared by different types of leukemias." (PMID 39450904, 2025). "Our findings suggest that the physical interaction between RUNX1 and the JMJD1C N-terminus may explain the functional importance of JMJD1C in leukemia." (PMID 39450904, 2025). "It has been shown that JMJD1C plays a role in several types of cancer, such as leukemia." (PMID 37491298, 2023). "The JMJD1C knockout also resulted in anemia in a mouse model of leukemia." (PMID 36429088, 2022). "Interestingly, JMJD1C has been reported to suppress leukemia cell growth by catalyzing H3K9 demethylation." (PMID 34586733, 2021).
leukemia (continued). "Furthermore, JMJD1C essentially contributes to MLL-AF9/HOXA9-mediated self-renewal of leukemia stem cells." (PMID 32625104, 2020). "The histone demethylase JMJD1C is overexpressed in patients with myeloproliferative neoplasms (MPNs) and has been implicated in leukemic stem cell function of MLL-AF9 and HOXA9-driven leukemia." (PMID 32017785, 2020). "High expression of ARID2, JMJD1C, MBNL1, MEF2C, or RUNX2 alone is associated with at least one indicator of poor prognosis in ALL patients, and CPEB2, MBNL1, RUNX2, and ZEB2 are all specifically overexpressed in MLL-FP leukemias." (PMID 28076791, 2017). "The inhibition of the (H3K9)‐demethylase JMJD1C, on the other hand, causes only minor defects with respect to blood homeostasis and has a minor influence on the self‐renewal of the hematopoietic stem cells with a simultaneous reduction of LSC frequency in MLL‐AF9‐ and HOXA9‐driven leukemias." (PMID 33289299, 2021). "Furthermore, JMJD1C suppresses leukemia cell growth by catalyzing H3K9 demethylation." (PMID 34586733, 2021). "It has been reported that Jmjd1c is a H3K9 demethylase, which is involved in the regulation of abnormal metabolic processes in different diseases such as leukemia and esophageal cancer." (PMID 40485981, 2025). "JMJD1C regulates aberrant metabolic processes in acute myeloid leukemia, contributes to MLL-AF9/HOXA9-mediated self-renewal of leukemia stem cells, and suppresses leukemia cell growth by catalyzing H3K9 demethylation." (PMID 37759870, 2023). "JMJD1C, a predicted histone demethylase at H3K9, was a top hit in two shRNA library screens in MLL-AF9 leukemia." (PMID 32806592, 2020). "For instance, JMJD1C functions as a co-activator for Runx1-Runx1T1 in acute myeloid leukemia cell lines and for HoxA9 in mixed lineage leukemia-AF9 and HoxA9-driven leukemia." (PMID 27649575, 2016). "In Chr 10q21, variations in JMJD1C are related to platelet count (P = 2.0 × 10-24), those in ARID5B with leukemia (P = 7.0 × 10-19), and those in C10orf107 with blood pressure (P = 2.0 × 10-18)." (PMID 25689165, 2015). "JMJD1C, the largest member of the Jumonji domain-containing lysine demethylase 3 (KDM3) family, is aberrantly expressed in various AML cells and is required for the survival of multiple types of leukemia." (PMID 39450904, 2025). "JMJD1C or the JMJD1C/RUNX1 interaction are such candidates for targeted therapies as JMJD1C is required for the survival of various leukemias but not for HSC homeostasis." (PMID 39450904, 2025). "GO analyses indicate that the JMJD1C and RUNX1 directly co-activated genes in MOLM-13 cells are involved in the cell cycle, DNA replication, and cell division processes, all of which are necessary to maintain the hyper-proliferation features and differentiation defects of leukemia cells." (PMID 39450904, 2025). "Indeed, several reports have noted that JMJD1C is not required for the survival and self-renewal of leukemia stem cells." (PMID 27649575, 2016). "Interestingly, RUNX2, MBNL1, JMJD1C, SENP6, MEF2C, and ZEB2 are also hypomethylated in MLL-FP samples compared to either normal cells or other leukemias (not shown)." (PMID 28076791, 2017).
acute myeloid leukemia (8 papers, 2016 to 2026). Acute myeloid leukemia (AML) is a group of neoplasms arising from precursor cells committed to the myeloid cell-line differentiation. "In this study, the positive regulatory effect of JMJD1C on glycolysis was observed in hypoxia-induced pulmonary hypertension, which was in accordance with that described in acute myeloid leukemia cells." (PMID 36934091, 2023). "Jumonji domain containing 1C (JMJD1C), which is a family member of lysine demethylase 3,10 has the capacity to regulate the aberrant metabolic processes in acute myeloid leukemia." (PMID 34586733, 2021). "JMJD1C has recently been shown to play a critical role in the survival of acute myeloid leukemia (AML) cells." (PMID 32017785, 2020). "JMJD1C, a histone demethylase, facilitates the preservation of leukaemic stem cells via epigenetic regulation, whereas RUNX1, a principal regulator of haematopoiesis, often displays mutations or dysregulation in acute myeloid leukaemia that hinder differentiation and lineage fidelity." (PMID 41492215, 2026). "JMJD1C (Jumonji Domain Containing 1C), a member of the lysine demethylase 3 (KDM3) family, is universally required for the survival of several types of acute myeloid leukemia (AML) cells with different genetic mutations, representing a therapeutic opportunity with broad application." (PMID 39450904, 2025). "Overexpression of KMD3C/JMJD1C promotes in vivo cell proliferation and tumorigenicity in a demethylase-independent manner, enhancing glycolytic and oxidative enzymes, which maintains leukemic cell bioenergetics and leads to severe acute myeloid leukemia (AML) characteristics." (PMID 37218871, 2023).
breast carcinoma (6 papers, 2013 to 2025). "Decreased expression of the JMJD1C variant, s-JMJD1C, was observed in breast cancer whereas in normal breast tissues the expression was significantly increased, suggesting its functions in tumor suppression." (PMID 30001383, 2018). "We showed that high JMJD1B or JMJD1C expression indicates poor prognosis in ovarian cancer patients, which has also been reported for breast cancer patients and therefore corroborates a pro-tumorigenic role of these epigenetic regulators." (PMID 39915607, 2025). "JMJD1C (Jumonji Domain Containing 1C) is a histone demethylase, tumor suppressor protein that is usually found to be reduced or lost in breast cancer." (PMID 35967849, 2022). "The tumor suppressor protein, BRCA1 and a histone demethylase called Jumonji Domain Containing 1C (JMJD1C), commonly reduced or lost in breast cancer are also suppressed in the E1-expressing cells." (PMID 34968392, 2021). "Interestingly, JMJD1C was observed downregulated in breast cancers compared to normal tissues, suggesting it as a potential tumor suppressor gene." (PMID 23496902, 2013).
cardiac hypertrophy (6 papers, 2020 to 2024). "The expression of JMJD1C mRNA and protein was increased during cardiac hypertrophy in humans and mice, which was associated with decreased methylation of H3K9." (PMID 32625104, 2020). "Protein synthesis is a hallmark of cardiac hypertrophy; thus, we tested the effects of JMJD1C on protein synthesis by performing [14C]-phenylalanine incorporation assay." (PMID 32625104, 2020). "Collectively, these findings demonstrated that JMJD1C was overexpressed in cardiac hypertrophy, which was associated with the downregulation of methylation of H3K9." (PMID 32625104, 2020). "Genes associate with cardiac hypertrophy included JMJD1C, ANXA7, TRIM8, NGB, and AKAP13." (PMID 36071494, 2022). "The inhibition of JMJD1C conversely reduces cardiac hypertrophy and fibrosis induced by angiotensin II and decreases TIMP1 transcription with pro-fibrotic activity." (PMID 39596076, 2024). "Jumonji domain-containing 1C (JMJD1C) is a histone demethylase that increases in expression during cardiac hypertrophy, leading to a decrease in H3K9 demethylation in humans and mice." (PMID 39596076, 2024). "Previous studies demonstrated that JMJD1C promoted the development of cardiac hypertrophy in angiotensin II-induced mice." (PMID 36934091, 2023). "JMJD1C is involved in pathological cardiac hypertrophy, in which its expression level increases, and H3K9 methylation decreases during cardiac hypertrophy in humans and mice." (PMID 34568453, 2021). "Taken together, here we identified JMJD1C as a new epigenetic regulator of cardiac hypertrophy by targeting the metabolic AMPK pathway." (PMID 32625104, 2020). "Next, we investigated the roles of JMJD1C in the regulation of cardiac hypertrophy using neonatal rat cardiomyocyte (NRCMs)." (PMID 32625104, 2020). "Here we demonstrate that JMJD1C serves as an epigenetic regulator that is involved in pathological cardiac hypertrophy." (PMID 32625104, 2020). "This confirms that AMPK signalling is involved in JMJD1C-mediated cardiac hypertrophy." (PMID 36555778, 2022). "Here, we investigate the roles of JMJD1C during cardiac hypertrophy in humans and mice." (PMID 32625104, 2020). "Here we observed that JMJD1C repressed the activation of AMPK during cardiac hypertrophy." (PMID 32625104, 2020). "Finally, our findings showed that AMPK activation with metformin blocked the effects of JMJD1C hyperexpression, whereas AMPK knockdown blockaded the effects of JMJD1C downregulation during cardiac hypertrophy." (PMID 32625104, 2020). "The roles of the histone demethylase JMJD1C in cardiac hypertrophy remain unknown." (PMID 32625104, 2020). "Histone demethylase JMJD1C, an important epigenetic factor, represses the activation of AMPK during cardiac hypertrophy through the reduction of CaMKK2 expression." (PMID 36555778, 2022).
myeloproliferative disease (4 papers, 2020 to 2025). "Since it was found to be overexpressed in patients with myeloproliferative neoplasms, JMJD1C is considered as a novel therapeutic target in these malignancies." (PMID 40282457, 2025). "The histone demethylases KDM4C (JMJD2C) and KDM3C (JMJD1C) were recently identified as signaling effectors of mutated JAK2 and target genes of the transcription factor NFE2, which is overexpressed in myeloproliferative neoplasms." (PMID 40140631, 2025).